CD68 (CD68 molecule)
Diseases named in the same sentence as CD68 in open-access papers (continued):
Sharing a sentence is not in itself a finding about the gene and the disease.
tumor (continued). "Further IHC exams stated that elements such as positive markers for histiocytes and monocytes (CD68+++ and CD14+), Langerine- and CD1a – could exclude HCL or another tumor with dendritic undetermined cells, that are usually Langerine -, but CD1a+." (PMID 29450403, 2017). "For CD68 infiltration there was a positive correlation with CD8+ T cell levels in tumour (r = 0.40; P = 0.01) but not stroma (r = 0.15, P = 0.34)." (PMID 28122336, 2017). "In agreement with the in vitro data, Vidatox promotes tumor growth as demonstrated by increased tumor volume and high Ki-67 labelled growth fraction in rat HCCs without affecting innate immunity evaluated by CD8, CD56 and CD68 expression." (PMID 28322221, 2017). "Consistent with the transcriptomic deconvolution analyses, the primary tumor demonstrated no T cell infiltration and was negative for PD-L1 and CD68." (PMID 28841418, 2017). "The negative correlations between R1 pre O2 and CD3- and CD68-stained tumour fractions and the positive correlation between ADC and CD68 tumour fractions may be explained by a possible increase in interstitial fluid associated with inflammation." (PMID 28550313, 2017). "As in non-neoplastic tissue, tumor-infiltrating CD68+ or HLA-DR+ cells were consistently negative for ZEB1, too." (PMID 28945795, 2017). "There were more CD68 positive cells in the tumour area of HPV+ compared to negative OPSCC (MWU, P = 0.01) and a non-significant increase in the stromal regions." (PMID 28122336, 2017). "In non-irradiated mice, the density of CD68+ cells present in the core of the tumor was about 29.5±6.5% of the tumor area." (PMID 29069812, 2017). "The tumour microenvironment also contains innate immune cells and we evaluated the expression of markers of neutrophils (NP57+), natural killer cells (CD56+) and macrophages (CD68+)." (PMID 28817839, 2017). "High infiltration of CD68+ TAM was significantly higher in males (p = 0.044) in I-type tumours and with absent vascular tumour growth (p = 0.018) in PB-type tumours." (PMID 28673320, 2017). "For HPV ̄ tumours sub-stratifying by median CD68 cell density into high versus low groups showed a significantly higher level of PD-L1+ expression (P < 0.0001), and density of both CD8+ T cells (P = 0.007) and CD68+PD-L1+ cells (P < 0.0001)." (PMID 28122336, 2017). "We also analyzed the infiltration of CD68- and CD163-positive macrophages in tumor tissue of AITL." (PMID 29100307, 2017). "Distinguishable from tumor-associated macrophages (TAM), we did not see expression of CD68, CD204 and CD206 expression on these cells." (PMID 29100353, 2017). "In addition, the relationship between CD68+ and CD163+ TAMs in the tumor microenvironment of adult cHL and other clinical characteristics was also examined." (PMID 27745550, 2016). "In addition, several studies focused on the tumor-promoting M2 phenotype using more specific markers, including CD163 and CD204, or double staining of CD68 and CD163." (PMID 27144518, 2016). "Significant differences in the localization pattern of immune cell density between the four tumor regions were confirmed for CD3+ (p = 0.002), CD4+ (p = 0.015), CD8+ (p = 0.006), CD20+ (p = 0.007), CD25+ (p = 0.008) and CD68+ (p = 0.010) cells by Friedman two-way ANOVAs." (PMID 27221038, 2016). "The data demonstrated that stabilin-1 is expressed on CD68+ TAM in TS/A tumor tissue but not on CD31+ micro-vessels." (PMID 27105498, 2016). "Similarly, we analysed the prognostic role of CD68 and CD20 according to the three tumor compartments (tumor, stromal and peripheral) separately, and also with regard to stromal morphology." (PMID 27637082, 2016). "Although the foamy macrophages around the tumor cells stained positively for CD68, the tumor cells were completely negative." (PMID 27506610, 2016).
tumor (continued). "A significant treatment interaction between a high ratio of CD56+ NK/NKT cells in relation to the sum of CD68+ and CD1a+ cells were seen in the whole cohort (p = 0.007) and in PB-type tumours (p = 0.012), but not in I-type tumours (data not shown)." (PMID 27275582, 2016). "CD73, in contrast, was most prominently expressed on fibroblast-like tumor stromal cells without showing a co-localization with cells expression the myeloid marker CD68." (PMID 27532024, 2016). "By immunohistochemistry, the tumor cells are positive for histiocytic markers including CD68, CD163, CD11c and so on, whereas negative for S-100 protein and CDla." (PMID 27535029, 2016). "We found that CD68 and EphA3 co-stain in a GBM tumor microenvironment indeed." (PMID 27494882, 2016). "Results demonstrated that IL-13 could be expressed by CD3, CD4, CD8, CD56, CD68 and CD20 positive cell respectively in ESCC tumor tissue." (PMID 26771842, 2016). "Of note, the CD163-positive macrophages may be more suitable to identify the TAMs than the CD68-positive macrophages in OSCC and the infiltration of CD163-positive macrophages in tumor may be more important for tumor progression." (PMID 26769084, 2016). "Further phenotypic characterization of stabilin-1 positive cells using monocyte/macrophage marker CD163 revealed that CD68+Stab-1+ TAM co-expressed CD163 in certain tumor areas whereas CD68−Stab-1+ cells were typically negative for CD163." (PMID 27105498, 2016). "Stromal and tumoral ALDH1 expression was evaluated immunohistochemically in BrCa and their lymph node metastases (LNMs), and related to clinico-pathological characteristics, patients’ outcome, presence of CD68, HLADR, retinoic acid (RA) in stroma, and selected proteins in tumor cells." (PMID 26305673, 2015). "Tumor samples from mice subjected to daily restraint stress had elevated MCP1 gene and protein levels, increased CD14+ cells, and increased infiltration of CD68+ cells." (PMID 25738355, 2015). "Despite lacking a concordant relation of S100A9 and CD68 expression (data not shown), the increase of S100A9 or CD68 in tumor stroma significantly reduced patient recurrence-free survival (Left, p = 0.012)." (PMID 26315114, 2015). "Tumor invasion and high density of CD68+ and CD34+ cells increased in SLN+ may reflect a tumor favorable microenvironment." (PMID 26218530, 2015). "To study the inflammatory cell infiltration, we quantified the average densities of CD68+ macrophages (pan macrophage marker), CD163+ macrophages (M2, tumor promoting macrophage marker), and toluidine blue+ mast cells in the surrounding tumor bearing prostate tissue (TINT) of all tumor types." (PMID 26536349, 2015). "Immunohistochemistry was positive for CD10 and CD68 and in situ hybridization revealed the expression of receptor activator of nuclear factor-kappa B (RANK) in the giant cells and receptor activator of nuclear factor-kappa B ligand (RANKL) in the tumor cells." (PMID 25793139, 2015). "In contrast, CD68+ cells are significantly reduced in EE in comparison with SE and are only detected in the tumour region, and not in healthy parenchyma." (PMID 25818172, 2015). "It showed that CD68+ cells in the tumor stroma but not in the tumor nest were an independent prognostic factor for decreased cancer-specific survival, accounting for the localization of TAMs in the tumors more than their mere presence." (PMID 26243145, 2015). "The CD68 antigen is expressed by all macrophages, neutrophils, basophils, DC, and myeloid progenitor cells (e.g., myeloid-derived suppressor cell), while CD163 is expressed by M2 (pro-tumor macrophages)." (PMID 26374556, 2015). "Importantly, number of genes responsible tumor immune responses and desmoplastic reaction; Mst1r, TGFβr1, TGFβr2, VEGFa, CSF-1, SDF-2, CD44, IL-6ra, PD1, CD68, CD163, fibronection and MMPs were significantly reduced." (PMID 26429877, 2015).
tumor (continued). "The expression pattern of all the factors (IL-6, IL-6R, gp130, and CD68) was not similar among the tumor tissues, such that all the factors were gradually up-regulated until five weeks." (PMID 26525581, 2015). "Instead, a concordant relation of CD68+ infiltrating cells with the CD34+ vessel number by IHC staining (rs = 0.277, p = 0.014) supported a positive role of infiltrated macrophages in tumor angiogenesis required for tumor growth and metastasis." (PMID 26315114, 2015). "In the multivariate analysis, only tumor recurrence and high abundance of CD68 in TIF irrespective of R-status proved to be independent prognostic indicators." (PMID 26497197, 2015). "In KO animals, tumors derived from galectin-3-expressing cells were infiltrated by CD68+-cells, whereas in tumors derived from galectin-3-nonexpressing-cells, CD68+ cells failed to infiltrate tumors and accumulated in the periphery of the tumor mass." (PMID 24421272, 2014). "In the present case, the tumor cells were positive for vimentin, CD68 and Ki-67, and negative for S-100, SMA, desmin, CD31, CD34, ALK and AE1/AE3." (PMID 24959221, 2014). "Gil-Bernabe and colleagues found that tumor-derived tissue factor (coagulation factor III or CD142) stimulated clot formation and enhanced subsequent tumor cell survival at the metastatic site by recruiting CD11b+/CD68+/F4/80+/CX3CR1+ macrophages." (PMID 25125485, 2014). "Confocal images revealed higher intensity of CHI3L1 expression in CD68+interstitial macrophages from tumor bearers, relative to normal mice." (PMID 24399973, 2013). "The Authors found that lymphatic vessel density in the invasive front was significantly higher for high CD163+/CD204+ tumor samples compared to low samples but not statistically significant difference was found between the high and low CD68+ infiltration." (PMID 23950747, 2013). "Notably, the morphological analysis demonstrated that TIM-3 was also present on CD68+ macrophages, CD31+ endothelial cells, CK-18+ epithelial cells, as well as on Bcl-2+ and PCNA+ tumor cells." (PMID 24137353, 2013). "The immunohistochemistry staining showed that the tumor cells were diffusely positive for S-100, CD1a, langerin and CD68, but negative for CD3, CD5, CD20, CD21, CD30, CD38, CD56, CD79a, ALK, HMB-45, Melan-A, pan-cytokeratin and MPO." (PMID 23388086, 2013). "In contrast, CD68 was negative in all tumour cells being only positive in clusters of histiocytes found in the papillary stroma." (PMID 24066870, 2013). "This tumor was classified as an undifferentiated myxoid sarcoma based on the lack of a glial proliferation, strong CD68 and vimentin immunolabeling in the majority of tumor cells and the absence of CD1a and GFAP immunolabeling." (PMID 24073000, 2013). "In addition, it is interesting our finding indicating that if there is a high CD68/(CD3+CD20) ratio at the invasive front, most of MICs with a positive MMP-11 or TIMP-2 phenotype at the tumor center are macrophages (respectively)." (PMID 23300781, 2012). "Moreover, intratumoral CD68+ density, intraepithelial TGF-β1 levels and EMT tumor profile correlated with high tumor grade." (PMID 22273460, 2012). "The result clearly shows that CD68+ TAMs are randomly distributed within the tumor without any preference for the hypoxia." (PMID 22888475, 2012). "We found that infiltration of CD163+ and CD68+ macrophages into tumor stroma, but not into tumor nest, were of clinical relevance." (PMID 22824040, 2012). "In addition, it is remarkable our finding indicating that if there is a high CD68/(CD3+CD20) ratio at the invasive front, most of MICs with a positive MMP-11 or TIMP-2 phenotype at the tumor center are macrophages." (PMID 23300781, 2012).
tumor (continued). "Moreover, immunofluorescence staining for the markers such as CD68 and F4/80 revealed that most of TAM is the tumor and metastasis-promoting M2-type." (PMID 21481239, 2011). "Two weeks after the CDL treatment, more than 90% of CD11b+/CD68+ TAM were depleted in the tumor region of the OUBC, whereas the CL treatment did not affect the number of CD11b+/CD68+ TAM in the tumor." (PMID 21481239, 2011). "Immunohistochemically, the tumor cells were positive for vimentin and focally for CD68, but were negative for the other antibodies tested in vivo." (PMID 21092322, 2010). "The expected model size with the highest performance level consists of 10 of the most robust predictive variables and is comprised of four clinico-pathological variables and six additional proteins: nodal status, tumor size, AURKA, BCL2, age, CD68, HER2, MYBL2, CCNB1 and GSTM1." (PMID 20809974, 2010). "The mononuclear tumor cells (MTCs) showed immunoreactivity with vimentin, Ki-67 and p 53 and were negative for CD-68 expression." (PMID 20976205, 2010). "Immunohistochemical analysis showed that CD68+ cells progressively colonized the tumor stroma, being almost absent in the healthy tissue, clearly present in pre-cancerous conditions, and peaking in samples from patients with adenocarcinomas." (PMID 21059221, 2010). "In high-grade serous tumors from optimally debulked patients, positive associations were seen between intraepithelial cells expressing CD3, CD4, CD8, CD45RO, CD25, TIA-1, Granzyme B, FoxP3, CD20, and CD68, as well as expression of MHC class I and II by tumor cells." (PMID 19641607, 2009). "Cells tumour was highly positive for vimentin and CD68 and negative for S100, factor XIIIa and CD34 and SMA." (PMID 20066060, 2009). "Cells tumour was highly positive for vimentin and CD68 and negative for S100, CD34, Factor XIIIa and SMA." (PMID 20066060, 2009). "Tumour area infiltration by macrophages (CD68) was not statistically different between the TAXHER01 and control groups." (PMID 16404427, 2006). "Diffuse macrophage infiltration (CD68) was significantly increased in HER2 controls compared with the treatment group, but increased macrophage infiltration was observed around the residual tumours in the treatment group." (PMID 16404427, 2006). "The three sections with no CD68 staining were full of tumour with no bone/tumour interface and hence had no osteoclasts present." (PMID 15812559, 2005). "Notably, the log odds ratio (LOD) of genus-level enrichment was nearly twofold higher in Rs, and this increase correlated with favorable features of the tumor immune microenvironment, including higher frequencies of CD8+ and CD4+ TILs, lower densities of CD68+ TAMs, and improved PFS." (PMID 41463268, 2025). "The expression levels of ALG3 in tumor cells and stromal cells were positively correlated with the abundance of CD4+ FOXP3+ regulatory T cells (Tregs), CD3+CD4+ T cells and PD-L1, whereas they were negatively correlated with the abundance of CD8+ T cells and CD68+CD86+ macrophages." (PMID 40475760, 2025). "CD68 expression has significant negative relation with tumor purity and significant positive correlation with tumor-infiltrating levels of B cell, CD4+ T cell, CD8+ T cell, macrophage, myeloid dendritic cell and has no relation with cancer associated fibroblast in ESCA." (PMID 40918116, 2025). "Interestingly, we found that the number of tumor infiltrating CD68+ macrophages and the ratio CD68+/CD8+ did not predict the outcome of post‐surgery treatment with SRL in patients that had been treated with SRLs also before surgery." (PMID 40789673, 2025). "Moreover, the CD68/CD163 ratio was significantly lower in the TC group demonstrating the prevalence of anti-inflammatory M2-macrophages producing a wide range of angiogenic and tumor-promoting growth factors, cytokines and chemokines." (PMID 39936166, 2025).
tumor (continued). "We used detailed methods to evaluate the composition of the tumor microenvironment, including CLR, infiltrating CD3+ and CD8+ lymphocytes, and the expression of checkpoint inhibition pathway proteins PD‐1/PD‐L1 on CD3 + lymphocytes, CD68+ macrophages, and tumor cells." (PMID 39783790, 2025). "CD68 expression has significant negative relation with tumor purity and significant positive correlation with tumor-infiltrating levels of CD8+ T cell, macrophage, myeloid dendritic cell and cancer associated fibroblast, has no relation with B cell, CD4+ T cell in PAAD." (PMID 40918116, 2025). "The results demonstrated that CD68 expression has significant negative relation with tumor purity and B cell, significant positive correlation with tumor-infiltrating levels of CD4+ T cell, CD8+ T cell, macrophage, myeloid dendritic cell and cancer associated fibroblast in COAD." (PMID 40918116, 2025). "However, ICB treatment did not affect the infiltration of FOXP3+ Tregs and CD68+ macrophages at any tumor sites (primary tumor and metastases)." (PMID 40591148, 2025). "Furthermore, an open-label phase 0 clinical trial involving six patients with metastatic BC showed promising results, with c-MET-CAR-T cell therapy leading to tumor necrosis, hemorrhage, and significant infiltration of T-cells (CD3+, CD4+, and CD8+) and macrophages (CD68+) at the injection sites." (PMID 40281554, 2025). "As such, the analysis revealed CD3+, CD20+ and CD68+ excluded tumours to have an increased MC compared to tumours with no immune cell presence (desert/cold) or with high levels of infiltration (hot), however should be interpreted with caution due to low sample size." (PMID 39420530, 2025). "However, ISG15+ CD68+ macrophages were not increased in tumours with ICI treatment when compared to treated‐naïve tumours, suggesting they were not dominant in the IFN‐γ response in the TME." (PMID 39934971, 2025). "Spatial breakdown of the transcriptomic data for CD68 and CD8 in CDKN2Adel and WT S-AOIs evidenced how their downregulation was not confined to specific areas but widely distributed across the entire tumor topography, confirming the systemic effect induced by the deletion." (PMID 40877968, 2025). "We should add that, among all the infiltrating immune cells examined, CD68+ macrophages dominated, and their number correlated with the number of other immune cells (e.g., stem cells, T and B lymphocytes), a lower expression of EMT markers, and a lower number of tumor buds." (PMID 40508145, 2025). "Moreover, the intra-T/peri-T Bcl-2+ cell ratio was significantly lower in the CD68+ than CD20+ cell compartment (0.6 ± 0.2 vs 1.3 ± 0.3, p = 1e-13) and Bcl-2+ cell count was lower in the macrophage than tumor cell compartment (292.9 ± 40.7 vs 228.7 ± 26.5, p = 4e-07)." (PMID 41415285, 2025). "In addition, immunohistochemical staining for ITGAL and multiplex immunofluorescence (mIF) staining for ITGAL, CD20, CD68, CD4, and CD8 from tissue microarrays containing 118 tumor tissues and paired paracancerous tissues from patients with NSCLC were performed." (PMID 38646528, 2024). "Positive correlation between AF of mast-cells and CD68+ macrophages inside and between regions (CD68+ cells in TC and CD117+ cells in IM) supports the findings that mast cells may also promote the attraction of monocytes into the tumor." (PMID 38287290, 2024). "Altogether, the expression of both markers Iba-1 and CD68 in the perivascular microenvironment of the peritumoral niche correlates with a favorable prognosis of patients related to low levels of CMA in PCs, revealing a potential use of these markers for monitoring tumor progression." (PMID 39796053, 2024). "In addition, CD3G+T cells ratio was significantly correlated with CD68 + macrophages, CD4 + T cells, and CD8 +T cells ratio, indicating it could play an important role in the anti-tumor immunity in DLBCL." (PMID 38980810, 2024).